NLRP3 (NLR family pyrin domain containing 3)
Diseases named in the same sentence as NLRP3 in open-access papers (continued):
Sharing a sentence is not in itself a finding about the gene and the disease.
heart disease (22 papers, 2016 to 2025). "The fusion and dysfunction of mitochondria play pivotal roles in the pathological changes associated with heart diseases, resulting in ROS accumulation, where ROS serves as an upstream regulatory factor within NLRP3 inflammasome activation." (PMID 38650918, 2024). "Regardless of a viral, autoimmune, or chemotherapy-induced trigger, many inflammatory cardiac diseases converge on NLRP3 activation and the release of pro-inflammatory cytokines such as IL-1β and IL-18." (PMID 40940808, 2025). "In cardiac fibrosis, various stimuli, including oxidative stress, mitochondrial dysfunction, and metabolic disturbances common in heart diseases, can activate NLRP3 inflammasomes." (PMID 39195221, 2024). "NLRP3 inflammasome emerges as a pivotal factor triggering cardiac inflammation, exerting unignorable influences on initiation and developing of heart diseases." (PMID 38650918, 2024). "Our article has underscored the pivotal role of NLRP3 inflammasome within heart injury and cardiac diseases pathological progression." (PMID 38650918, 2024). "NLR family pyrin domain‐containing 3 (NLRP3)/IL‐1β signaling axis has been demonstrated to mediate S100a8/a9‐induced myelopoiesis in heart disease." (PMID 38023700, 2023). "The NLRP3 inflammasome is a vital mediator of inflammatory responses, and plays a crucial part in heart diseases." (PMID 36327403, 2022). "And differentially polarized macrophages shaped by the cardiac environment (including hormone-orchestrated local cytokine milieu, ER stress, NLRP3 inflammasome activation) have major roles in determining the outcome of CVB3-induced heart disease." (PMID 29868513, 2018). "Although there is evidence suggesting that exercise may reduce NLRP3 inflammasome activation in heart disease and AD, the specific effects of exercise on the NLRP3 inflammasome in PD remain unclear." (PMID 40192010, 2025). "In addition, the NLRP3/Caspase-1/IL-1β pathway is present in the inflammatory response in heart disease." (PMID 39640484, 2024). "Moreover, This article elucidates the mechanism by which blocking NLRP3 inflammasome activation via ANS can be utilized to regulate the treatment of heart disease." (PMID 38650918, 2024). "Targeting the Nlrp3 inflammasome and/or mitochondria may be a therapeutic approach for Ang II-induced cardiac diseases." (PMID 33628380, 2021). "Targeting the Nlrp3 inflammasome and/or mitochondria may be a therapeutic strategy in Ang II-induced cardiac diseases." (PMID 33628380, 2021). "The importance of the NLRP3 inflammasome in cardiac disease has been broadly investigated." (PMID 29850631, 2018). "Since it has been proven that the NLRP3 inflammasome is crucial in the pathological progression of various cardiac diseases, numerous experiments have been conducted to verify different approaches targeting either the NLRP3 inflammasome or its upstream regulators and downstream effectors." (PMID 29850631, 2018). "Moreover, an animal study conducted on NLRP3 −/− mice indicated enhanced inflammatory markers, but cardiac aging was prevented by the NLRP3 ablation, thus confirming that some heart disorders may be related to the NLRP3 complexes." (PMID 34070553, 2021). "The expressions of pyroptosis-related NLRP3, GSDMD, caspase-1, IL-1β, and IL-18 in these heart disease patients were elevated." (PMID 35647057, 2022). "We focused on the relationship between the two biomolecules namely NLRP3 (rs4612666) and CARD8 (rs2043211) with gum and heart disease." (PMID 34199122, 2021). "Hence, VNS may realize therapeutic objectives in treating heart diseases by diminishing the expression of α1-AR and β-AR in the SNS, thereby inhibiting NLRP3 inflammasome pathway." (PMID 38650918, 2024).
central nervous system diseases (20 papers, 2016 to 2025). "In central nervous system diseases, NLRP3 expression in microglia is a proximal cause of pyroptosis." (PMID 39887961, 2025). "NLRP3 inflammasome is associated with numerous CNS disorders, from sterile acute brain injuries to chronic neurodegenerative diseases." (PMID 36160384, 2022). "Recent studies have demonstrated that NLRP3 expressed in microglia may be a proximal cause of pyroptosis in central nervous system diseases." (PMID 39887961, 2025). "In conclusion, the NLRP3 inflammasome plays a critical role in the pathogenesis of several CNS disorders by serving as a bridge between innate immunity and neuroinflammation." (PMID 40075143, 2025). "It has been reported that pathological neuroinflammation were associated with TXNIP in some central nervous system disorders, especially via the TXNIP/NLRP3 pathway." (PMID 40388874, 2025). "The secretion and maturation of IL-1β is regulated by the inflammatory activation of NLRP3, which induces various forms of inflammatory response, thereby promoting the development of central nervous system diseases." (PMID 38127000, 2023). "Studies have demonstrated a close link between the NLRP3 inflammasome and central nervous system diseases." (PMID 36406365, 2022). "Recent research has indicated a strong link between the NLRP3 inflammasome and central nervous system diseases." (PMID 36406365, 2022). "There is a growing body of literature on the expression of NLRP3 in central nervous system diseases." (PMID 35676979, 2022). "This study systematically evaluated the role of NLRP3 inflammasome in CNS disorders using bibliometric analysis through 1,217 papers from the WoSCC database during the last decade." (PMID 36160384, 2022). "Recent reports evidence that NLRP3 inflammasome plays important mediating roles in inflammation and innate immunity response in central nervous system diseases." (PMID 34257822, 2021). "The NOD-like receptors (NLR) family pyrin domain containing 3 (NLRP3) inflammasome is a key player in initiating the inflammatory response in various central nervous system disorders entailing TBI." (PMID 34506597, 2021). "The NLRP3 inflammasome plays a crucial role in coordinating host physiology and shaping the peripheral and central immune and inflammatory responses of central nervous system diseases." (PMID 34327209, 2021). "The exact molecular mechanisms on the assembly, activation, and regulation of NLRP3 inflammasome are required to be further examined, which are very important for NLRP3 inflammasome to be as a novel therapeutic strategy in CNS disorders." (PMID 27652274, 2016). "Therefore, understanding the role of the NLRP3 inflammasome in the occurrence of neuroinflammation and the pathological process of central nervous system diseases is important." (PMID 40075143, 2025). "On the other hand, the development of specific inhibitors or modulators targeting the NLRP3 inflammasome and its upstream and downstream pathways may become a new strategy for the treatment of central nervous system diseases." (PMID 40075143, 2025). "Due to their anti-oxidative and anti-inflammatory nature, Nrf2 inducers have attracted attention for inhibiting NLRP3 inflammasome activation in numerous NLRP3 inflammasome-related CNS disorders, especially the natural compounds that have been studied comprehensively." (PMID 35418995, 2022). "Besides, many other CNS disorders, such as prion diseases, experimental autoimmune encephalomyelitis (EAE), are associated with the activation of NLRP3 inflammasome." (PMID 27652274, 2016). "Therefore, there is still considerable interest in identifying a small molecule NLRP3 inhibitor that has the potential of increasing efficacy, reducing side effects, and could be used to manage NLRP3-related neuroinflammatory and CNS disorders." (PMID 36160384, 2022).
central nervous system diseases (continued). "Importantly, the importance of the NLRP3 inflammasome in neuroinflammation should not be ignored, and more research is necessary to determine how its activation mechanisms are related to CNS disorders." (PMID 40075143, 2025). "However, despite decades of research, our understanding of NLRP3 inflammasome in central nervous system diseases is still lacking." (PMID 36160384, 2022).
liver (20 papers, 2015 to 2026). "The current review summarizes mechanisms and pathways of pyroptosis, outlining the involvement of NLRP3 inflammasome-mediated pyroptosis in digestive system tumors." (PMID 37081882, 2023). "The four pathways of pyroptosis and the role of NLRP3 inflammasome-mediated pyroptosis in digestive system tumors are reviewed below with the intention of aiding progress in the treatment of digestive tract-related tumors." (PMID 37081882, 2023).
brain diseases (19 papers, 2014 to 2025). "On the other hand, NLRP3 inflammasome promotes pyroptosis of “bystander” CD4+ T cells and causes brain disease and neuroinflammation that are closely associated with NLRP3 inflammasome activation in microglia." (PMID 37465759, 2023). "Activation of the NLRP3 inflammasomes pathway is responsible for neuroinflammation and is associated with several brain diseases." (PMID 35335908, 2022). "NLRP3 is a subcellular multiprotein complex that is expressed in the central nervous system (CNS) and it is responsible for neuroinflammation and associated brain disease." (PMID 35335908, 2022). "Hence, the NLRP3 inflammasome is often implicated in the pathology of brain diseases." (PMID 32445196, 2020). "Background/Objectives: Chronic inflammation and inappropriate NLRP3 inflammasome regulation are related to many brain diseases." (PMID 40732240, 2025). "The NLRP3 inflammasome is emerging as a central player in brain disorders and systemic conditions with neurological repercussions, underscoring its relevance within the CNS and potential as a biomarker." (PMID 41357236, 2025). "The following paragraphs will delve into the main advances concerning the NLRP3 inflammasome, followed by specific paragraphs about its role in most relevant brain diseases, a discussion of the results, and a conclusion." (PMID 37189617, 2023). "Inhibiting the NLRP3 inflammasomes has been a tantalizing enterprise given its potential therapeutic applications in brain diseases." (PMID 37189617, 2023). "As monocytes/macrophages and microglia strongly express the NLRP3 inflammasome, the latter is involved in human brain diseases and is the most intensely studied and popular inflammasome." (PMID 37189617, 2023). "Given the involvement of neuroinflammation in a considerable number of brain diseases, several promising NLRP3 inhibitors have been investigated." (PMID 35204211, 2022). "Altogether, these data demonstrate that NRs such as ERs, Rev-erbs, and GR play a regulatory role on NLRP3-induced brain disease such as cerebral ischemia, epilepsy and depressiveness." (PMID 33716981, 2021). "Microglial inflammation driven by the NACHT, LRR and PYD domain‐containing protein 3 (NLRP3) inflammasome contributes to brain disease and is a therapeutic target." (PMID 32445196, 2020). "The NLRP3 inflammasome is emerging as a pathway modulated by sex hormones, which exert context-dependent effects and contribute to vulnerability or resilience in brain disorders." (PMID 41357236, 2025). "Hence, in this study, we aimed to elucidate the mechanisms associated with NLRP3, BBB disruption, and neutrophil infiltration and their impact on the progression of brain disease." (PMID 40413505, 2025). "Current literature suggests that the NLRP3 inflammasome plays an important role in many brain disorders and could be altered by resveratrol intake." (PMID 37375772, 2023). "In addition, NLRP3 increases the levels of proinflammatory factors and accelerates pathological progression in a variety of brain disorders." (PMID 37375772, 2023). "Of interest, in an attempt of understanding the role of NLRP3 inflammasome in the pathophysiology of CNS diseases, several efforts have been made to implement research on the effects of NLRP3 gene deletion and its components in preclinical models of brain disorders." (PMID 31200447, 2019). "Regarding the release of IL-1β from microglia in response to HIV-1 or FIV infections and its relationship to pathogenesis, the multivariate analyses of FIV-infected animals suggested that elevated expression of caspase-1, NLRP3 and IL-1β contributed to the development of brain disease." (PMID 24886384, 2014). "However, no proof is hitherto available that NLRP3 inhibition would be a human brain disease-modifying approach." (PMID 37189617, 2023).
retinopathy (18 papers, 2016 to 2025). "Inflammation in retinopathy has been widely linked to the NLRP3 inflammasome, with recent studies suggesting that aberrant connexin 43 (Cx43) hemichannel activity sits upstream of its assembly." (PMID 38970061, 2024). "On the contrary, high expression of miR-126 is associated with a lower activity of NLRP3, reducing inflammation related to retinopathies and induced brain damage in the mouse diabetic model." (PMID 36139749, 2022). "To decipher the mechanism whereby microglia elicits its pathogenic effects in BLE-induced retinopathy, we sought to identify the NLRP3 inflammasone and IL-1β that provoke retinal destruction in mice." (PMID 27831552, 2016). "In order to highlight a unique targeted method to treat HR, we investigated the effects of FO as a protective agent on SIRT1/NLRP3 in Ang II-induced retinopathy." (PMID 38360728, 2024). "In our study, we found FO enhanced SIRT1 expression and reduced NLRP3 activation and retinopathy and dysfunction in Ang II-treated mice and mRECs." (PMID 38360728, 2024). "Here, we discovered that FO therapy decreased NLRP3 activation, retinopathy, and dysfunction while increasing SIRT1 expression." (PMID 38360728, 2024). "Following MCC950 therapy, we observed that NLRP3 and IL-1β expression were suppressed, and that in Ang II-infused animals, NLRP3 suppression reduced retinopathy and dysfunction." (PMID 38360728, 2024). "Given the link between Cx43 and the NLRP3 inflammasome in retinopathy, we recently explored the relationship between these two proteins in chronic kidney disease." (PMID 38970061, 2024). "An MMF-mediated increase in HO-1 and a concomitant decrease in caspase-1, IL-1β, TNF-α, and in NLR family pyrin domain containing 3 (NLRP3) was also described in albino BABL/c mice exposed to bright white light for one hour to mimic light-induced retinopathy." (PMID 36552824, 2022). "The activation of NLRP3 by DAMPs has been reported in various retinal disorders such as endophthalmitis, uveitis, glaucoma, ischemic retinopathies, DR, AMD, and IRDs." (PMID 35269741, 2022). "We further found an increased co-location of NLRP3, Iba-1, and IL-1β in fluorescence and a concomitant increased protein expression of NLRP3, caspase-1, and IL-1β in western blotting in chronic blue light-induced retinopathy." (PMID 27831552, 2016). "To elucidate the effect of microglia in chronic light-induced retinopathy, we performed our experiment on Ccr2−/− mice with a focus on NLRP3 inflammasome activation in microglia." (PMID 27831552, 2016). "Collectively, our data demonstrated that activated microglia and the cellular NLRP3 inflammasomes contributed to the severity of BLE-induced retinopathy." (PMID 27831552, 2016). "FO may improve SIRT1 expression and decrease NLRP3 activation in retinopathy and dysfunction brought on by Ang II, and the effects were consistent across both in vivo and in vitro models." (PMID 38360728, 2024). "Interestingly, P2X7−/− mice were protected from the NaIO3-induced retinopathy and inflammatory NLRP3, IL-1β and IL-6 gene expression in the retina." (PMID 36671003, 2023). "Retinopathy in NLRP3-AID is a surprising finding that deserves attention, as it could help deepen the understanding of this disorder." (PMID 37480029, 2023). "DAMPs function through multiple specialized innate immune receptors, such as receptors for advanced glycation end products (RAGE), toll-like receptors (TLRs) and the NOD-like receptor (NLRs) family, purine receptor 7 (P2X7), NLR pyrin domain 3 (NLRP3), in retinal disorders." (PMID 35269741, 2022). "This study further supports our hypothesis that microglial NLRP3 inflammasome activation may be a mediator of IL-1β-related photoreceptor degeneration in light-induced retinopathy." (PMID 27831552, 2016).
retinopathy (continued). "The objectives of the present study were to report four newly recognized kinds of retinopathy in NLRP3-AID patients, as well as to provide all the ophthalmologic manifestations of NLRP3-AID in a single-center cohort of NLRP3-AID patients diagnosed after 2015." (PMID 37480029, 2023). "Retinopathy and dysfunction were lessened by MCC950 target-induced NLRP3 inflammasome activation, while overexpression of SIRT1 had the opposite impact on NLRP3 inflammasome activation, indicating that SIRT1 functions as an upstream regulator of NLRP3 activity." (PMID 38360728, 2024). "FO may mitigate Ang II-induced retinopathy and dysfunction via modulating the expression of SIRT1/NLRP3." (PMID 38360728, 2024). "Moreover, the activation of microglia and their cellular NLRP3 inflammasomes occurred as an earlier step before the structural and functional damage of the mice retinas, which collectively supported that microglial NLRP3 inflammasome might be the key to the chronic blue light-induced retinopathy." (PMID 27831552, 2016). "Considering the very little quantity of the transcribed protein of NLRP3 inflammasone and IL-1β in RPE–choroid complex, here we supposed that microglia might make much more contributions to the BLE-induced retinopathy in mice." (PMID 27831552, 2016).
hematological diseases (14 papers, 2019 to 2024). "Caspase-3 was found to be abnormally expressed in leukemia patients, while the NLRP3 inflammasome has been shown to be associated with the incidence of blood disorders." (PMID 34801085, 2021). "NLRP3 inflammasome has been widely implicated in the development and progression of various hematological diseases." (PMID 31428046, 2019). "Furthermore, it was shown that the deregulation of the NLRP3 inflammasome can cause hematopoietic diseases." (PMID 39223663, 2024). "In addition to MDS, the NLRP3 inflammasome has also been implicated in the pathogenic phenotype of other hematological diseases." (PMID 33525345, 2021). "Previous studies have shown that the NLRP3 inflammasome is involved in the development of hematologic diseases and plays a role in regulating hematopoiesis." (PMID 38764093, 2024). "Despite a plethora of data regarding solid tumors, NLRP3 inflammasome’s implication in the pathogenesis of hematological malignancies only recently gained attention." (PMID 38397043, 2024). "Altogether, these results show the potentially universal role of the NLRP3 in the pathogenesis of hematological diseases." (PMID 35897704, 2022). "Comprehensive future studies are needed to investigate the potential use of NLRP3 inhibitors in NLRP3-driven hematological diseases." (PMID 33525345, 2021). "Until recently, little was known about the influence of the NLRP3 inflammasome on hematopoietic malignancies; however, the importance of the NLRP3 inflammasome is becoming increasingly evident in hematological diseases." (PMID 33525345, 2021). "Studies have demonstrated that the NLRP3 inflammasome is involved in the incidence of blood disorders, implying that it plays a role in hematopoiesis regulation." (PMID 34801085, 2021). "In hematological malignancies, the role of NLRP3 inflammasome in normal and malignant hematopoiesis has been lately reviewed." (PMID 32733479, 2020). "For KRAS-driven hematological malignancies, a therapeutic approach might include the use of NLRP3 and IL-1R suppressors." (PMID 36902299, 2023). "An open question remains how the NLRP3 inflammasome activation drives hematological malignancies, whether by a cell-autonomous signal that promotes cell proliferation directly or via a modification of the TME or both." (PMID 32733479, 2020). "In summary, the data suggest NLRP3 and IL-1R inhibition as a strategy for the treatment of KRAS-driven hematological malignancies." (PMID 32246016, 2020).